CLRN2 (clarin 2)
Description:
Plays a key role to hearing function. Required for normal organization and maintenance of the stereocilia bundle and for mechano-electrical transduction.
Synonyms: DFNB117
Tractability: Antibody: UniProt predicts a signal peptide or a membrane-spanning region; its Gene Ontology location is reachable by antibodies, with medium confidence.
Gene: Protein-coding gene on chromosome 4 (17,515,165 to 17,527,104, forward strand). Ensembl gene ENSG00000249581.
Subcellular location: Cell projection, stereocilium membrane
Gene Ontology:
Molecular function: protein binding
Biological process: sensory perception of sound; auditory receptor cell stereocilium organization; stereocilium maintenance
Cellular component: stereocilium bundle; stereocilium membrane
Genetic constraint (gnomAD): Loss-of-function variants: 17 observed, 21.43 expected, observed/expected ratio (o/e) 0.79, 90% interval 0.54 to 1.19. The upper end of that interval is the gene's LOEUF score, 1.19, which puts it in group 5 of 6, group 1 being the genes least tolerant of losing a copy. Missense variants: 288 observed, 312.79 expected, observed/expected ratio (o/e) 0.92, 90% interval 0.83 to 1.01. Synonymous variants: 140 observed, 133.76 expected, observed/expected ratio (o/e) 1.05, 90% interval 0.91 to 1.2.
Gene-disease validity (ClinGen):
ClinGen rates the evidence that CLRN2 causes each of these diseases.
nonsyndromic genetic hearing loss (autosomal recessive): Moderate.
Homologues: Orthologues: chimpanzee CLRN2 (98% identical), macaque CLRN2 (97% identical), dog CLRN2 (96% identical), mouse Clrn2 (94% identical), pig CLRN2 (94% identical), rat Clrn2 (94% identical), guinea pig CLRN2 (93% identical), rabbit CLRN2 (91% identical), tropical clawed frog clrn2 (62% identical), zebrafish clrn2 (50% identical), Caenorhabditis elegans Y67D8C.22 (18% identical), Drosophila melanogaster CG1103 (17% identical). Paralogues in human: CLRN1 (35% identical), CLRN3 (24% identical).
Diseases named in the same sentence as CLRN2 in open-access papers:
CLRN2 is named in the same sentence as 9 diseases in open-access papers, as found by Europe PMC text mining. Sharing a sentence is not in itself a finding about the gene and the disease. The quoted sentences say what the papers report.
deafness (4 papers, 2019 to 2026). An inherited or acquired condition characterized by the complete loss of the ability to hear from one or both ears. "On one hand, this is not surprising, as there are other examples of genes with a clear causal association with deafness that have been reported to be mutated in just one family, such as CLRN2." (PMID 36689403, 2023). "Clinical and genetic analyses of an extended consanguineous family with pre-lingual, moderate-to-profound autosomal recessive sensorineural hearing loss, allowed us to identify CLRN2, encoding a tetraspan protein, as a new deafness gene." (PMID 33496845, 2021). "We identify CLRN2 as a novel deafness gene in human and zebrafish and describe a new deafness-causing allele in mice." (PMID 33496845, 2021). "Utilizing an unbiased forward genetic screen, we have identified an ENU‐induced Clrn2 mutation as the cause of deafness in the clarinet mouse mutant (Clrn2clarinet)." (PMID 31448880, 2019). "We showed, for the first time, that CLRN2 is a deafness-causing gene in humans." (PMID 33496845, 2021). "In this study, we establish that Clrn2 is a novel deafness gene associated with progressive hearing loss in both mice and humans, and as such, severe loss‐of‐function CLRN2 mutations should be considered in the aetiology of human autosomal recessive hearing loss." (PMID 31448880, 2019). "Featuring CLRN2 as a new human deafness gene, future genetic screenings of hearing impaired families worldwide will probably unveil additional CLRN2 families and provide important clues about associated clinical phenotype progression and severity." (PMID 33496845, 2021). "Together, our findings identify CLRN2 as a new deafness gene, which will impact future diagnosis and treatment for deaf patients." (PMID 33496845, 2021). "We demonstrate that Clrn2 is a novel deafness gene required for maintenance of transducing stereocilia in the sensory cochlear hair cells." (PMID 31448880, 2019). "Utilizing a large‐scale forward genetic screen in mice, genome mapping and gene complementation tests, we identified Clrn2 as a new deafness gene." (PMID 31448880, 2019). "By revealing a functional, compensatory interplay between clarin-1 and clarin-2, this study reframes CLRN1-associated deafness as a network-dependent disorder and provides a mechanistic basis for genetic stratification and therapeutic directions in USH3 and related sensorineural hearing loss." (PMID 41572507, 2026).
hearing loss (4 papers, 2019 to 2026). "Mutations of other genes also lead to loss of the shorter stereocilia associated with hearing impairment, for example the Baiap2l2 mutant and the Clrn2 mouse mutant." (PMID 35727972, 2022). "In regard to the observed progressivity of the hearing impairment in clarinet mice, the earliest reported clinical diagnosis of hearing loss of the CLRN2 affected individuals in the family we present is between 2 and 3 years of age." (PMID 33496845, 2021). "Altogether, while mutations in CLRN1 unambiguously lead to USH3A, current findings suggest that CLRN2 mutation most likely causes non‐syndromic hearing loss." (PMID 31448880, 2019). "Altogether, this further confirms that variants in CLRN2 can lead to sensorineural hearing loss." (PMID 33496845, 2021). "Perhaps it may be that “mild” CLRN2 hypomorphic mutations, such as p.Leu113Val may represent, is likely to predispose to a progressive, late‐onset hearing loss phenotype." (PMID 31448880, 2019). "Utilizing data from the UK Biobank study, we could show that CLRN2 is involved in human non‐syndromic progressive hearing loss." (PMID 31448880, 2019). "CLRN2 variants may exacerbate hearing loss in USH3 patients, supporting inclusion of CLRN2 in genetic screening." (PMID 41572507, 2026).
Usher syndrome (1 paper, 2019). A syndromic diseae characterized by the association of sensorineural deafness (usually congenital) with retinitis pigmentosa and progressive vision loss. "However, given the interspecies difference in phenotypic presentation observed with Clrn1, we cannot exclude the possibility that pathogenic CLRN2 mutations in humans might give rise to an Usher syndrome‐like phenotype." (PMID 31448880, 2019).
genetic diseases (1 paper, 2021). "With respect to the aberrantly spliced CLRN2 transcripts, variants that disrupt splicing machinery signals are recognized as significant contributors to human genetic diseases, with variants shown to impact accurate recognition and removal of intronic sequences from pre-mRNA." (PMID 33496845, 2021).
CLRN2 also shares sentences with these, for which no sentence is quoted: autosomal recessive hearing loss (2 papers); hearing (1); Hearing impairment (1); sensorineural hearing loss (1); Tinnitus (1).